INS (insulin)
Diseases named in the same sentence as INS in open-access papers (continued):
Sharing a sentence is not in itself a finding about the gene and the disease.
renal failure (continued). "Transplantation can also be considered in insulin-dependent type 2 diabetic patients with renal failure who have a body mass index < 30 kg/m2 with low insulin requirements (<1 U/kg of body weight)." (PMID 37176684, 2023). "As mentioned, it has also been reported that kidney [18F]FDG uptake is related to the degree of sensitivity to insulin and that renal failure indirectly impairs this sensitivity and therefore glucose metabolism." (PMID 38248741, 2023). "When renal failure is present and transplantation is being considered, it is crucial to identify behaviors tied to insulin restriction, often seen in serious psychosomatic conditions like eating disorders and affective disorders." (PMID 38152359, 2023). "Studies have found that there is impaired insulin response and insulin resistance in the occurrence of acute kidney injury." (PMID 38054182, 2023). "In patients with renal failure, insulin clearance is delayed; this can protect against developing DKA in ESKD." (PMID 35673321, 2022). "It is recommended that patients with hyperkalaemia treated with insulin therapy should be monitored for up to six hours following therapy since the glucose lowering effect of insulin is prolonged in patients with kidney failure." (PMID 35552566, 2022). "A previous study noted that in patients hospitalized due to an acute kidney injury, hypoglycemic events were most common in insulin users." (PMID 35189851, 2022). "Considering renal function in the clearance of insulin, renal insufficiency affects glucose homeostasis and alters insulin metabolism." (PMID 35187079, 2022). "The proband’s daughter has 24 years of diagnosis and presents polyneuropathy, renal insufficiency and retinopathy, and has been treated with insulin therapy (10 U/day) with poor glycemic control." (PMID 35592779, 2022). "Since kidney failure can lead to gluconeogenesis and affect insulin resistance, it can be a contributing factor to increased PTH." (PMID 34505755, 2021). "There were effect modifications from renal insufficiency and insulin use on the relationship between SH and subsequent ESRD events." (PMID 33619302, 2021). "In patients with severe renal failure (eGFR < 30 mL/min/1.73 m2), insulin-based therapy is recommended to improve blood glucose control." (PMID 32489427, 2020). "The increase in insulin signaling corresponds to the literature, in which it was shown, that inhibition of insulin signaling delays the onset of kidney failure." (PMID 33281613, 2020). "Meanwhile, the presence of insulin abnormalities in patients with renal failure has been known for a relatively long time." (PMID 33270683, 2020). "As for the relationship of the kidney with insulin, insulin metabolism and excretion become delayed with progressing renal failure." (PMID 33270683, 2020). "In T2DM patients with severe renal failure and HbA1cabove target, insulin-based therapy is the recommended choice to improve blood glucose control." (PMID 32489427, 2020). "In patients with severe renal failure, insulin-based therapy is recommended to improve blood glucose control." (PMID 32489427, 2020). "Although she temporarily required dialysis and high doses of insulin, within 1 month NS and acute kidney injury had been alleviated by oral prednisolone and low-density lipoprotein apheresis." (PMID 32967631, 2020). "Although insulin is considered the best agent to improve glycemic regulation in patients with renal failure, there is limited data about the differences in insulin profiles and their impact on minimizing GV." (PMID 31886089, 2019). "Use of insulin or insulin secretagogues, polypharmacy, coexisting comorbidities, renal insufficiency, dehydration, impairment of counter-regulatory responses represent the main predisposing risk factors for hypoglycemic episodes." (PMID 30833929, 2019).
renal failure (continued). "There is a paucity of data regarding ideal insulin preparations in DKD subjects owing to the lack of pharmacokinetic-pharmacodynamics studies for various insulin preparations in subjects with varying magnitudes of renal insufficiency." (PMID 31890395, 2019). "GSK3 inhibition increases glucose uptake in insulin-insensitive muscle and adipose tissue, while it reduces albuminuria and glomerulosclerosis in acute kidney injury." (PMID 29244860, 2017). "In contrast, exogenous insulin does not undergo the first-pass effect in the liver, the kidney plays an important role in the metabolism and clearance of circulating insulin in patients with renal failure." (PMID 27471550, 2016). "Similar to the results in the 5/6-nephrectomized rat model, the PK properties of BIL have been shown to be unaffected by renal insufficiency in humans, whereas insulin undergoes substantial renal clearance." (PMID 27528391, 2016). "The search for the combination of keywords related to short- and long-acting insulin analogs yielded a few studies in patients with renal insufficiency." (PMID 26872083, 2016). "Errors involving insulin can lead to hospitalisation, MAOIs have potential for severe drug-drug interactions, opioids have reduced clearance in cirrhosis and increased risk of constipation and hepatic encephalopathy, and NSAIDs may contribute to renal impairment and hepatorenal syndrome." (PMID 27618841, 2016). "Insulin is generally recommended when renal failure is advanced, linagliptin being a potential alternative." (PMID 23841986, 2013). "Our results showed that the administration of MCP-1 along with insulin into diabetic mice with moderate kidney failure restored the blood glucose, creatinine, urea nitrogen and urine albumin to physiological levels." (PMID 23451253, 2013). "Infective or inflammatory disease (P3, 4, 5), severe illness requiring intensive care (P10, 12, 39), kidney failure (P34, 37, 56, 67) and corticosteroid therapy (many instances) tended to increase patients’ insulin requirements while adrenal insufficiency reduced requirements (P46)." (PMID 40973362, 2025). "Additional contributing factors may include increased glucose consumption, altered glucose supply and insulin degradation in hepatic or kidney failure, and, theoretically, heightened insulin sensitivity." (PMID 40150028, 2025). "Furthermore, many variables such as liver failure, kidney failure, and response to insulin can influence a physician’s choice of insulin therapy and the subsequent outcomes." (PMID 38919469, 2024). "Another subject with MODY HNF-1B had to be initiated on insulin in a context of infection and acute renal failure, and could reverse back to oral medication afterwards." (PMID 38331895, 2024). "Therefore, in clinical treatment, patients with concurrent renal insufficiency are more likely to use insulin for blood sugar control." (PMID 39533550, 2024). "Likewise, we found that some patients considered discontinuing treatment because they believed insulin was related to blindness, renal failure and even limb amputation; they believed these conditions were not part of the disease progression." (PMID 37377235, 2023). "Dapagliflozin as well as insulin treatments markedly reduced the observed kidney failure." (PMID 36986825, 2023). "In addition, the analysis of our results suggests that C-peptide, the product of insulin metabolism, is a possible valid biomarker that shows the proper functioning of blood glucose levels overall in patients with renal failure." (PMID 35204630, 2022). "Nicotinamide mononucleotide and nicotinamide are currently under investigation in healthy and patient populations for their potential beneficial effects on cardiac function, surgery-related acute kidney injury, glucose tolerance, insulin sensitivity, and cardiorespiratory fitness." (PMID 35620522, 2022).
renal failure (continued). "In hypoglycaemic only participants, infection (n = 15; 34%), overmedication with prescribed hypoglycaemic agents (sulphonylureas and insulin) (n = 11, 25%), inadequate food intake (n = 9; 20.5%) and acute renal failure (n = 7, 15.9%) were the main reasons for presentation." (PMID 34703733, 2021). "In a similar series of patients, sRAGE levels were associated with circulatory and kidney failure and a higher rate of mortality but were not affected by insulin therapy." (PMID 32760352, 2020). "However, there are a number of factors and misconceptions that make Malaysian patients reluctant to initiate insulin therapy such as fear of pain and injections, risks for kidney failure, and the perception that insulin therapy indicates end stage diabetes." (PMID 33378349, 2020). "Eventually, depression of insulin clearance occurs in patients with renal insufficiency." (PMID 33270683, 2020). "However, challenging patients such as those with high insulin requirements, renal failure, or use of glucocorticoids were excluded from the study." (PMID 31261760, 2019). "The presence of insulin in association with the IGF-I pathway demonstrated in our studies may indicate with some probability, that IGFBP-7 could be a potential biomarker of acute kidney injury in dogs with babesiosis." (PMID 31801572, 2019). "Information about the choice of various preparations of insulin and about differences in insulin profiles along with their impact on glycemic variability is still limited because only a few studies have examined patients with advanced renal insufficiency." (PMID 31886089, 2019). "Furthermore, this animal exhibited signs of stress, evidenced by high plasma epinephrine and glucagon concentrations, prior to the insulin clamp in addition to renal failure." (PMID 30540820, 2018). "Our results indicate that the glycoprotein composition of important HDL-associated proteins does indeed successfully differentiate between clinical groups across the range of insulin sensitivity from normal, to pre-diabetic, to diabetic with renal failure, especially Apo C-III isoforms." (PMID 28287093, 2017). "She took insulin regularly but still had eye problems, heart disease and died of kidney failure." (PMID 28327202, 2017). "It remains to be elucidated whether insulin aggravates the impact of HCV infection on patients with DM with regards to the progression of renal failure." (PMID 26817874, 2016). "Additionally, renal failure impairs the clearance and metabolism of antidiabetic agents and insulin, thus frequently necessitating reassessment of prescriptions or adjustment of doses 48,70." (PMID 26872083, 2016). "However, the effect of renal failure on insulin kinetics in critically ill patients is still unclear due to the lack of pharmacokinetic studies on insulin secretion and clearance related to HD treatment." (PMID 25750607, 2015). "Insulin can also be used safely in patients with renal failure." (PMID 24427312, 2014). "Other authors have reported that, in the absence of exogenous UII, palosuran potentiated glucose-induced insulin release in perfused rat pancreas and decreased 24-hour urinary albumin excretion rate in diabetic patients with renal failure with regard to their disease progression." (PMID 21559414, 2011). "If so, then our results would be remarkable in the sense that, for patients scoring R, I or F, a relatively short period of postoperative BGL control would have such an effect on renal failure (90% of patients were treated with the Aalst Glycemia Insulin Protocol in the ICU for less than 46.0 h)." (PMID 19055829, 2008). "Therefore, we evaluated the effect of both intra- and postoperative tight blood glucose control (80 to 110 mg/dL) with continuous intravenous insulin on the incidence and severity of acute kidney injury after cardiac surgery, using the RIFLE criteria." (PMID 19055829, 2008). "Insulin therapy may be necessary for optimal glucose control in patients with renal failure." (PMID 40760593, 2025).
renal failure (continued). "Insulin has the advantage of being effective when combination therapy with other agents fails to achieve the glycaemic goal and improved glycaemic control can protect against microvascular complications that may lead to blindness and renal failure." (PMID 31271255, 2019). "Insulin may be used in any stages of renal insufficiency and is the best agent for this purpose." (PMID 29527102, 2018). "Chronic insulin treatment did not influence the mortality risk at 90 days when corrected for baseline differences in age, gender, malignancy and renal insufficiency (HR 1.10, 95 % CI 0.72, 1.69) nor when corrected for the APACHE IV score (HR 0.87, 95 % CI 0.58, 1.30)." (PMID 27495247, 2016). "Thus, the data may well represent rates of recovery in proinsulin, C-peptide, and insulin levels after endogenous stimulation by sulfonylurea ingestion in renal failure." (PMID 26664768, 2015). "In patients at risk for acute kidney injury (that is, patients scoring R, I or F but without the need for dialysis), mean creatinine level between hospital admission and discharge increased by 25% in the Control group but not in the Insulin group." (PMID 19055829, 2008). "Although ongoing advancements in insulin therapy have improved management of T1D, insulin therapy does not fully prevent complications, and patients with T1D have an increased risk of cardiovascular disease, foot ulcers and amputations, diabetic retinopathy, and kidney failure." (PMID 37766096, 2023). "Driven by the lack of insulin or ineffective production of insulin in the pancreas, high blood sugar gives rise to many life-threatening diabetic complications and makes DM a leading cause of cardiovascular morbidity and mortality, renal failure, amputations, and blindness." (PMID 35265148, 2022). "Insulin treatment for T1DM was continued, and hemodialysis was initiated on day 2 and continued three times per week because of acute kidney injury." (PMID 32967631, 2020). "Moreover, renal failure not clinically apparent may result in an increased risk of ADRs, especially in water-soluble drugs, such as insulin and glibenclamide." (PMID 29618951, 2018). "In more advanced stages of renal failure, when the GFR reaches less than 15-20 cc/min, renal clearance of insulin decreases." (PMID 28497087, 2017). "Specifically, renal insufficiency resulting in elevated apoC-III, or LpB:C-III, presumably via insulin resistance triggers the chain of inflammatory events." (PMID 21829457, 2011). "Patients with severe concomitant diseases, who are mainly excluded from randomized, prospective, cardiovascular trials, such as CABG, severe renal insufficiency (GFR between 25 and 50 ml/min/1.73 m2), patients receiving insulin treatment are all represented in this trial." (PMID 40753226, 2025). "Additional experiments and clinical research are required to understand the effects of insulin among individuals with CKD because enough data is not easily obtainable for renal failure patients." (PMID 36111327, 2022). "Concerning risk perceptions, our findings showed that few adherents perceived insulin adherence would delay long-term complications (like renal failure) but not short-term complications (like microalbuminuria)." (PMID 38515508, 2022). "Prescribing incorrect insulin or metformin doses, not adapting the dose of a medication for renal insufficiency and not keeping to the maximum daily dose recommendations were some of the dosing problems reported in the reviewed studies." (PMID 35776376, 2022). "In one UC patient, a mediterranean dietary regimen was suggested after 15 days, long-acting insulin after 75 days and short-acting insulin after 90 days of treatment; in this patient, metformin was not prescribed due to renal failure." (PMID 31313243, 2020). "In addition, surrogate insulin sensitivity indexes, such as the HOMA-IR, can be influenced by renal retention of these metabolites in the setting of kidney failure." (PMID 29762478, 2018).
renal failure (continued). "Our results demonstrated a clear reduction of insulin-stimulated glucose transport in CKD muscles which is likely attributable, at least in part, by the down-regulation of muscle GLUT4 glucose transporter expression in kidney failure." (PMID 28459862, 2017). "Regardless of the insulin considered as the best choice to improve glycemic control in patients with renal failure, specific information about dose adjustment and differences in insulin profiles in this population is still missing." (PMID 26872083, 2016). "Insulin regimens did not affect blindness (RR: 1.10, 95 % CI: 0.76 to 1.60), or renal failure or doubling of serum creatinine level (RR: 0.68, 95 % CI, 0.43 to 1.06), compared to placebo or diet alone." (PMID 27391319, 2016). "These investigators found that lack of insulin therapy, hypoalbuminemia, higher mean blood pressure, and lower hemoglobin at baseline were independent predictors of kidney failure." (PMID 15985177, 2005). "Thus, individuals with pituitary, adrenal or renal insufficiency should not participate in multiple-day DF, whereas insulin- or thyroid hormone-dependent patients have to reduce their doses and be closely monitored." (PMID 40585323, 2025). "However, some studies showed that HOMA‐IR were not suitable for estimating insulin sensitivity in the unselected T2DM population such as the Renal Insufficiency and Cardiovascular Events (RIACE) cohort, because of the effect of exogenous insulin." (PMID 38225901, 2024). "Moreover, a theoric model has been proposed that showed that the more severe the renal failure is, the more overestimated the standardized uptake value (SUV) is, unless the renal failure indirectly impairs tissue sensitivity to insulin and hence glucose metabolism." (PMID 38248741, 2023). "The lowered blood glucose level rather than the insulin dose was related to reduced mortality (p < 0.0001), critical illness polyneuropathy (p < 0.0001), bacteremia (p = 0.02), and inflammation (p = 0.0006) but not to prevention of acute renal failure." (PMID 38068801, 2023). "Furthermore, insulin does not decrease relevant microvascular outcomes such as blindness or renal failure either." (PMID 27391319, 2016). "Administration of exogenous insulin fails to mimic the physiological activity of the islet and disease progression may lead to the development of serious complications such as kidney failure, retinopathies and vascular diseases." (PMID 27400873, 2016). "The glycerol content in insulin among patients with renal insufficiency may not be overlooked." (PMID 39997036, 2025). "Similarly, α-glucosidase inhibitors (acarbose and miglitol) are also contraindicated in patients with renal failure, whereas the non-sulfonylurea insulin secretagogues repaglinide and nateglinide can be used in patients with renal failure without dose adjustments." (PMID 24427312, 2014).